CD28 (CD28 molecule)
Diseases named in the same sentence as CD28 in open-access papers (continued):
Sharing a sentence is not in itself a finding about the gene and the disease.
tumor (continued). "CTLA-4 is a co-inhibitory receptor associated with suppression of anti-tumor immune responses and has a higher affinity than CD28 for binding CD80." (PMID 31959281, 2020). "CD8+CD28- T cell senescence is triggered by a variety of biological processes including telomere damage, Treg cells and tumor-associated stresses." (PMID 31181772, 2019). "Dendritic cell, T cell and tumor-associated expression of B7/CD28 and TNFR superfamily ligands and receptors." (PMID 30788290, 2019). "Opposite effects were observed when the Lck-binding motif of CD28 was mutated in tumor models in which TGFβ, which accumulates in the tumor tissue, was the factor mediating T-cell suppression." (PMID 31315298, 2019). "Inhibitory PD-L1/PD-1 signaling was blocked while providing CD28 costimulation led to augmented antitumor efficacy with decreased susceptibility to tumor-induced hypofunction." (PMID 29364163, 2018). "Concordant with observations in peripheral T cells, tumor associated CD4+ T cells retain higher levels of CD28 expression than CD8+ T cells." (PMID 30400835, 2018). "Our previous work demonstrated that a soluble factor from tumor cells is able to induce a suppressor phenotype (SP) in human CD8+ T cells typified by loss of CD27/CD28 expression and acquisition of a potent suppressor function." (PMID 28806909, 2017). "An additional promising approach demonstrated that exogenous IL-7 added to T cells co-cultured with tumor cells inhibited loss of CD28, a feature of replicative senescence, and allowed normal proliferative capacity and IL-2 production." (PMID 27809856, 2016). "The levels of CD4+Foxp3+ cells had a negative impact on adoptive immunotherapy and immune responses that is consistent with the increased anti-tumor effect of CAR-T with deleted lck domain of CD28 linked to IL-2 production." (PMID 26999211, 2016). "CARs are engineered proteins incorporating intracellular motifs from signaling molecules such as CD3ζ and CD28, alongside regions for antigen recognition (generally a single-chain variable fragment, scFv, generally from antibodies against tumor-associated or -specific antigens)." (PMID 40867541, 2025). "However, simultaneous treatment of mice with PD-L1 and CTLA-4 antibodies allows for restored expression of CD80 on tumor-associated DCs, leading to increased CD28 costimulation, downstream T cell responses, and reduced overall tumor burden." (PMID 39879305, 2025). "Whereas naïve lung and blood mostly contained differentiated NK cells, metastatic lungs harbored a large cluster of tumor-associated NK cells (Tumor NK) expressing markers of less differentiated NK cells (Emb, Cd27, Ccr2, Cd28, Thy1 or Sell), confirming our flow cytometric data." (PMID 41145419, 2025). "Similarly, in CAR T cells, CD28 was linked to robust short-term tumor lysis, heightened sensitivity, and reactivity to modestly expressed, including on-target off-tumor, antigens." (PMID 39792660, 2025). "Consistent with previous studies, TET2 and DNMT3A mutations were observed in non‐tumor cells including myeloid or B‐cells, suggesting early founding mutation in a progenitor cell in a subset of cases, but other mutations like IDH2, RHOA, and CD28 appeared to be tumor‐specific." (PMID 40510016, 2025). "Third-generation CAR-T cells carry two costimulatory domains, most frequently combining CD28 and 4-1BB, which may lead to the quicker expansion of T cells and more rapid elimination of tumor cells, but also causes CAR-T cells to remain longer in the host." (PMID 38927948, 2024). "Some researchers suggest that the chronic stimulation of cancer antigens leads to the cycle activation of the immune cells, which eventually causes CD8+CD28− T lymphocytes to proliferate and exert negative regulatory functions, thus inhibiting the tumor-killing effect of CTL." (PMID 37206348, 2023).
tumor (continued). "Tumor-infiltrating MDSCs harvested from TREM1-deficient mice exhibited diminished suppressive capacity on the proliferation of CD3+ T cells activated with anti-CD3/anti-CD28 compared with their TREM1-positive counterparts." (PMID 37651197, 2023). "➢ Trispecific T cell engager – The trispecific approach involves targeting CD3+ T cells along with two different tumor associated antigens, or targeting CD3 and CD28 on the T cell along with the tumor associated antigen to enhance specificity, lower toxicity, and improve T cell activation." (PMID 37304291, 2023). "A decrease in the ZP magnitudes of CaP coatings deposited at 200–250 V was strongly associated with elevated hTERT expression in tumor-derived Jurkat T cells preliminarily activated with anti-CD2/CD3/CD28 antibodies and then contacted in vitro with CaP-coated samples for 14 days." (PMID 34279263, 2021). "Compared to the second-generation CAR which contains a single costimulatory domain (CD28, 4-1BB or OX-40), the third-generation CAR contains two or more costimulatory domains which can exhibit strong short-term anti-tumor activity associated with CD28 and long-term persistence with 4-1BB." (PMID 34579759, 2021). "Based on our data, a decrease in the ZP magnitudes of CaP coatings deposited at 200–250 V was strongly associated with elevated hTERT expression in tumor-derived Jurkat T cells preliminarily activated with anti-CD2/CD3/CD28 antibodies and then contacted in vitro with CaP-coated samples for 14 days." (PMID 34279263, 2021). "In addition, CAR-T cells that express PD-1 dominant-negative receptors or chimeric PD-1:CD28 switch-receptors have been reported to increase anti-tumor effects and reduce susceptibility to tumor-induced T cell dysfunction." (PMID 32903593, 2020). "Loss of CD27/CD28, which has been described as a hallmark of ageing, could be partially responsible for decreased tumor infiltration by CD8+ cells observed in the older patients of our cohort." (PMID 33024560, 2020). "Therefore, in circumstances where long term CAR T cell persistence can cause severe off tumor toxicity, short-lived CARs can be designed by incorporating CD28 co-stimulatory domains." (PMID 30713539, 2018). "In conclusion, CD28 may be a tumor suppressor gene and rs3116496 polymorphism of CD28 gene showed positively correlation with the increased risk of BC." (PMID 29089469, 2017). "CD28-deficient NK cells were shown to have markedly reduced ability to lyse tumor cells." (PMID 25964782, 2015). "In addition, CD28-deficient NK cells were shown to have markedly reduced ability to lyse syngeneic tumor cells." (PMID 25964782, 2015). "However, none of the neutralizing antibodies or 1-MT blocked the induction of T-cell senescence and loss of CD28 induced by tumor cells." (PMID 25231413, 2014). "We have confirmed that B7-1/CD28 signaling at the effector phase of immunity is required to enhance T-cell based immune response against Lass5 antigen expressed by TAP-deficient tumor cells, and this requirement can be overcome when the targets express high levels of the Lass5 antigen." (PMID 25383875, 2014). "Furthermore, the loss of CD28 expression in naïve CD4+ T cells induced by tumor cells was significantly alleviated when they were separated in the Transwell system." (PMID 25231413, 2014). "Mechanistically, loss of co-stimulatory signals like HVEM/CD28 could impair antigen presentation of new tumor antigens generated by high TMB, while the immune-suppressive microenvironment mediated by B7-H3 may counterbalance the immune recognition advantage from genomic instability." (PMID 40699765, 2025). "CD28 and 4-1BB co-stimulatory domains induce distinct responses, with CD28 being responsible for rapid proliferation, stronger activation of effector functions, and greater secretion of inflammatory cytokines, while 4-1BB is linked to longer persistence and durable tumor control." (PMID 41228246, 2025).
tumor (continued). "These cells continue to express CD28, suggesting retained activation potential under certain conditions; however, their immune function is impaired by PD-1 expression, resulting in a loss of cytotoxicity and proliferation capacity and rendering them less effective at eliminating tumor cells." (PMID 40534863, 2025). "Therefore, our current dual-targeting BiCisCAR design strategy not only provides both CD28 and 4-1BB co-stimulation signaling for improved T-cell activation, but also allows for simultaneous targeting of two tumor-associated antigens to prevent potential tumor escape." (PMID 39043633, 2024). "Finally, the comprehensive mechanisms underlying the prognostic role of pTCD8+CD28- and its effect on tumour progression remain unclear, necessitating further exploration." (PMID 38519706, 2024). "CARs are composed of an extracellular single-chain variable fragment (scFv) that recognizes diverse tumor-associated antigens (TAAs), a transmembrane fragment, a CD3ζ T cell activating domain, and a costimulatory domain, such as the intracellular domains of CD28 and 4-1BB." (PMID 30777106, 2019). "The increased Akt activation by lenalidomide treated XBP1-CTL during tumor recognition may be associated with costimulatory signaling molecule CD28, a critical regulator of T cell proliferation and important for T cell activation and effector cells development." (PMID 27668268, 2015). "This study provides a highly translatable, cancer-specific nanomedicine platform, confirming that selectively antagonizing tumor-intrinsic CD28 holds profound promise for advanced cancer immunotherapy." (PMID 42261788, 2026). "In Jurkat xenograft models, SAp-CD28 demonstrated potent antitumor activity, and its combination with cytarabine resulted in near-complete tumor suppression, highlighting its potential for T-ALL treatment." (PMID 41926668, 2026). "In functional assays, co-culture of sorted M-MDSCs from AT3 tumor-bearing mice with anti-CD3/anti-CD28 activated T cells resulted in a lower suppressive effect of Pgdfl/flLysMCre M-MDSCs compared to Pgdfl/fl M-MDSCs on both CD4+ and CD8+ T cells." (PMID 41535266, 2026). "By leveraging elevated lysophosphatidylcholine acyltransferase (LPCAT) uptake mechanisms inherent to malignant cells, LPC-LNPs efficiently deliver Cd28 small interfering RNA directly to tumor cells while strictly avoiding T cell sequestration." (PMID 42261788, 2026). "Risk factors include high tumor burden, severe or early onset CRS, CD28‐based co‐stimulation, older age, and preexisting neurological disease comorbidities." (PMID 41207679, 2026). "Risk factors include high tumor burden, rapid in vivo CAR T‐cell expansion, elevated baseline inflammatory markers, and possibly the use of CD28 costimulation." (PMID 41207679, 2026). "In this study, we developed an enzyme-responsive self-assembling peptide, SAp-CD28, designed to target CD28 and undergo receptor-mediated self-assembly in the tumor microenvironment." (PMID 41926668, 2026). "When incorporated as building blocks into a trispecific T cell engager (Tri-TCE) targeting DLL3, CD3, and CD28, the anti- CD28 VHHs conferred superior tumor specific cytotoxicity compared to a bispecific T cell engagers (Bi-TCEs) targeting only DLL3 and CD3." (PMID 42079579, 2026). "This humanized construct effectively induced antigen-specific cellular immune responses and suppressed tumor growth in CD28/4-1BB/CD27 triple-humanized mice." (PMID 42079630, 2026). "PD-1 blockade enhanced the cytotoxicity of peripheral blood mononuclear cells (PBMCs) against tumor cells with high expression of PD-L1, an effect dependent on CD28 expression on T cells." (PMID 41941486, 2026). "An additional study demonstrated that adding the CD28 signaling domain before the ZAP70KD resulted in a construct capable of inducing tumor remission comparable to a BBζ CAR and more durable than a 28ζ CAR in a Nalm6 tumor mouse model." (PMID 41601693, 2026).
tumor (continued). "CAR-T cells engineered with 4-1BB or CD28 co-stimulatory domains have demonstrated significant anti-tumor activity." (PMID 40821789, 2025). "We compare CD19-targeting CAR-T cells comprising either a CD28 or a 4–1BB costimulatory domain, and found the former controlled the tumor burden better initially, while the latter reduced the frequency of tumor relapse." (PMID 40568128, 2025). "We selected B7-H3 as our first CD28 TCE target because it is expressed at high levels across many tumor types yet still detected at lower levels in some normal tissues." (PMID 39301613, 2025). "CTLA-4 primarily regulates T-cell activation at the priming stage in tumour-draining lymph nodes involving CD28-mediated T-cell co-stimulation, while PD-1 inhibition primarily occurs at the tumour site during the effector phase." (PMID 41462864, 2025). "Senescent T cells are characterized by the loss of CD27 and CD28 costimulatory molecules and the acquisition of a senescence-associated secretory phenotype (SASP), which suppresses immunity and facilitates tumor progression." (PMID 40136325, 2025). "Mock T cells, CT103a, and nanoCAR-T-cell types were activated using CD3/CD28 beads and IL-2 for 8 days before being co-cultured with tumor cells." (PMID 41439964, 2025). "CD28 costimulation also plays a crucial role during the activation of antigen-experienced T cells such as tumor-specific effector T cells, and the rescue of exhausted CD8+ T cells by PD-1–targeted therapies." (PMID 40402149, 2025). "The first signal is a tumor antigen; the second signal is a co‐stimulating factor, such as CD28; and the third signal is a proinflammatory cytokine." (PMID 40574416, 2025). "Exhausted CD8+ T cells rely on CD28 co-stimulatory signals for self-renewal and play a pivotal role in tumor immune evasion." (PMID 40534863, 2025). "GZMB, secreted by CD8+ cytotoxic T lymphocytes (CTLs), induces tumour cell apoptosis, and co‐stimulatory molecule CD28 is crucial for the proliferation, activation, cytokine production and development of CD8+ T cells." (PMID 40356247, 2025). "The focus lies on the impact of the native tumor microenvironment on CD8+ T cell activation after anti‐CD3/CD28 or anti‐PD‐1 treatment." (PMID 40952312, 2025). "In mouse models of colorectal cancer and melanoma, they found that the CD28/B7 co-stimulatory pathway is essential for effective PD-1 therapy during tumor burden and chronic viral infections." (PMID 40385461, 2025). "The 3D-tumor models were cocultured with CD28- or 4-1BB-costimulated L1CAM-CAR T or untransduced T cells." (PMID 41394860, 2025). "For example, the secretion of IFNγ at the tumor‐border across all donors after treatment with anti‐CD3/CD28 ranged from 440 to 60,000 pg/mL." (PMID 40952312, 2025). "To better explore the effects of TAK‐228 in the presence of the immune system, we co‐cultured tumor cells with PBMC from healthy donors previously activated with anti‐CD3/CD28." (PMID 39258533, 2025). "This control antibody, in marked contrast to XmAb808s, did not increase the antitumor activity of EpCAM×CD3 or boost T-cell counts, highlighting the requirement for CD28 engagement to generate tumor-targeted costimulation." (PMID 39301613, 2025). "We first explored the combination of targeted CD28 costimulation with a tumor-targeted Signal 1 provided by the EpCAM×CD3 bispecific antibody." (PMID 39301613, 2025). "Moving forward, there is a need to develop more accurate CAR-T evaluation models to assess the anti-tumor efficacy of CD28-modified CAR-T cells, including metrics such as tumor-killing ability, differentiation, persistence, and exhaustion." (PMID 40181986, 2025). "CD28 is crucial not only for anti-tumor T cell proliferation but also for developing and maintaining Tregs." (PMID 40143377, 2025). "In the A549 tumor model, while only two mice in the traditional MSLN CAR-T group exhibited near-complete tumor clearance, all mice in the NKG2D/CD28& MSLN CAR-T group achieved full tumor clearance." (PMID 40181405, 2025).
tumor (continued). "In the preclinical settings evaluated here, we found the overall tumor behavior for all mice treated with either CD19.4–1BB CAR-T cells or CD19.CD28 CAR-T cells to be indeed statistically different." (PMID 40568128, 2025). "Constructs such as SAR442257, a CD38/CD3 × CD28 trispecific antibody, leverage CD28 signaling to promote robust T-cell activation and sustained anti-tumor responses." (PMID 40508128, 2025). "In the PDO1 and T cell co-culture model, the anti-CD3/CD28 positive control group exhibited the strongest ability to kill tumor cells." (PMID 39979981, 2025). "In a spatially defined and functional manner, we have also demonstrated that T cells in both non‐tumor as well as tumor‐border tissue respond to polyclonal activation via anti‐CD3/CD28." (PMID 40952312, 2025). "Here, we demonstrate that XmAb808 induces CD28-mediated T-cell costimulation in a tumor antigen–dependent fashion." (PMID 39301613, 2025). "Elevated incidence of CD20+ T-cells in MGUS and MM and the expression of CD8, NKG2D, and CD28 suggests anti-tumor functionality." (PMID 40079005, 2025). "XmAb808 is a tumor-selective XmAb 2 + 1 BsAb targeting B7-H3 on tumor cells and CD28 co-receptor on T cells, thus designed to activate CD28 only in the presence of tumor cells." (PMID 40565299, 2025). "Our study shows that NKG2D/CD28&CAR-T cells exhibit enhanced cytotoxicity against tumor cells, especially those with low antigen density, both in vitro and in vivo." (PMID 40181405, 2025). "Direct interactions involve physical contact between immune and tumor cells, mediated by membrane-bound ligands and their respective receptors, including stimulatory and inhibitory signaling molecules like CD28, CD80, PD-1, and PD-L1." (PMID 40649953, 2025). "One limitation of this study is that we cannot distinguish between host-derived and tumor-derived signals (only in CD28 expression due to IHC evaluation), making interpretation challenging." (PMID 41155258, 2025). "Then these pre-activated, effector cells were co-cultured with the target tumor cells (4T1-turbo and N2C-eGFP) in the context of a peptide mixture and anti-CD28 antibody in 96-well plates to induce antigen-specific lytic responses." (PMID 41050655, 2025). "These bispecific antibodies monovalently engage tumor antigens to promote clustering of CD28 at the immune synapse, leading to potent T-cell costimulation." (PMID 39301613, 2025). "Recently, anti-CTLA4 therapy has been used successfully to re-invigorate T cell-mediated anti-tumour immune responses by blocking CTLA4-mediated suppression of CD28 function." (PMID 40496752, 2025). "In summary, our study suggests that NKG2D/CD28&CAR-T cells maintain anti-tumor functionality under chronic antigen stimulation in both MSLN and CD19 CAR-T models." (PMID 40181405, 2025). "In contrast, NKG2D/CD28&CD19 CAR-T cells demonstrated stronger tumor control, with complete clearance observed in a subset of treated mice." (PMID 40181405, 2025). "These APCs support tumor-infiltrating T cells and provide CD28 co-stimulation during PD-1 blockade therapy, enabling sustained antitumor immune responses and facilitating the efficacy of PD-1 blockade." (PMID 40385461, 2025). "Patients stratified into high and low groups based on the proportion of tumor-infiltrating CD28+PD1−/CD8+ T cells using a cut-off value of 1.55% demonstrated that the high-proportion group had prolonged PFS (p = 0.018)." (PMID 40136325, 2025). "In summary, the scFV, hinge region, transmembrane region, and signal transduction region can be comprehensively optimized in combination with tumor specificity and individual patient differences to develop a CD28-based CAR with the best overall performance." (PMID 40181986, 2025). "Further refinements led to third-generation (3G) CARs, which combine multiple co-stimulatory signals (e.g., CD28 plus 4-1BB) in an attempt to further amplify anti-tumor efficacy." (PMID 41154636, 2025).